HMGB1 (high mobility group box 1)
Diseases named in the same sentence as HMGB1 in open-access papers (continued):
Sharing a sentence is not in itself a finding about the gene and the disease.
mesothelioma (continued). "HMGB1 was overexpressed in tumor tissue, but not correlated with overall survival of mesothelioma." (PMID 33230247, 2020). "Notably, They found that HMGB1 was present in the pleural lavage of rats treated with MWCNT-7, a rigid MWCNT, but not in rats treated with DWCNT, and the lack of HMGB1 in the pleural cavity was also observed in the DWCNT-treated rats that developed mesothelioma." (PMID 41003038, 2025). "In fact, HMGB1 stimulates the secretion of TNF-α from macrophages and activates protumoral factors such as NF-κB, leading to chronic inflammation, autophagy and mesothelial cell transformation; thus, targeting HMGB1 may be an additional potential therapy for mesothelioma." (PMID 36232554, 2022).
endothelial dysfunction (36 papers, 2012 to 2026). In vascular diseases, endothelial dysfunction is a systemic pathological state of the endothelium (the inner lining of blood vessels) and can be broadly defined as an imbalance between vasodilating and vasoconstricting substances produced by (or acting on) the endothelium. "Biochemical studies have shown that TMAO-associated endothelial dysfunction occurs via high mobility group box-1 (HMGB1), an inflammatory mediator." (PMID 39337693, 2024). "This review summarizes the main features of dengue infection and describes the known causes associated with endothelial dysfunction, highlighting the involvement and possible relationship between HMGB1 and DENV." (PMID 36016387, 2022). "Our results suggest that high concentrations of UA cause endothelial dysfunction via the HMGB1/RAGE signaling pathway." (PMID 28116308, 2017). "In patients with type 1 diabetes, serum HMGB1 levels were positively associated with markers of low-grade inflammation and endothelial dysfunction." (PMID 23118492, 2012). "HMGB1 may be a therapeutic target for treatment or prevention of endothelial dysfunction and associated cardiovascular diseases." (PMID 31336567, 2019). "The present study tested whether TMAO associated endothelial dysfunction results via HMGB1 activation." (PMID 31336567, 2019). "In addition, HMGB1 levels were positively associated with markers of low-grade inflammation and endothelial dysfunction." (PMID 23766563, 2013). "Increased visfatin production has been linked to high mobility group box 1 (HMGB1), which enhances inflammatory processes in the arteries and contributes to endothelial dysfunction." (PMID 40170859, 2025). "Our previous work demonstrated that extracellular HMGB1 exacerbates inflammation and endothelial dysfunction in diabetic corpus cavernosum through the receptor for advanced glycation end products (RAGE)/NF-κB signaling pathway." (PMID 41281764, 2025). "Endothelial cells are vulnerable to the damaging effect of Hcy and HMGB-1, which can promote endothelial dysfunction and initiate atherogenesis." (PMID 37513606, 2023). "In conclusion, our results demonstrate that HMGB1 is one of the important mediators of TMAO-induced endothelial dysfunction." (PMID 31336567, 2019). "In this regard, the present study for the first time found that TMAO upregulated HMGB1 expression, and such increased HMGB1 contributes to the TMAO associated endothelial dysfunction." (PMID 31336567, 2019). "In this regard, high-mobility group box protein 1 (HMGB1), an inflammatory mediator, has been reported to disrupt cell–cell junctions, resulting in vascular endothelial hyper permeability leading to endothelial dysfunction." (PMID 31336567, 2019). "Treatment of HUVECs with a high concentration of UA results in increased mRNA expression and extracellular release of HMGB1, which induces proinflammatory responses and endothelial dysfunction." (PMID 28116308, 2017). "Interactions between RAGE and HMGB1 stimulate oxidative stress and inflammatory response, leading to endothelial dysfunction." (PMID 28116308, 2017). "In conclusion, the present study indicated that high concentrations of UA induce endothelial dysfunction by the HMGB1/RAGE signaling pathway." (PMID 28116308, 2017). "HMGB1-TLRs interaction can activate the NFκB signaling pathway, and activated NFκB plays a significant part in inflammatory phenotypic changes in endothelial dysfunction and various heart diseases." (PMID 27070323, 2016). "In vitro experiment has shown that AGEs induced endothelial dysfunction via HMGB-1-mediated inflammation and oxidative stress in human umbilical vein endothelial cells." (PMID 27847406, 2016). "There is a paucity of data examining the role of TLR2 and 4 in glucose and HMGB1 induced endothelial dysfunction." (PMID 25303153, 2014). "Uric acid induces endothelial dysfunction also by activating the HMGB1/RAGE signaling pathway." (PMID 40559381, 2025).
endothelial dysfunction (continued). "It has been suggested that the high mobility group box 1 protein (HMGB1) may be involved in endothelial dysfunction." (PMID 36016387, 2022). "Interestingly, treatment of sera with ethyl pyruvate (EP, an inhibitor of HMGB1) significantly reduced endothelial permeability, demonstrating that HMGB1 is one of the mediators of early detection of endothelial dysfunction during the infectious process." (PMID 36016387, 2022). "Future studies are necessary to further test this hypothesis, validating the targeted regulation of HMGB1 by miR-505 in relation to its implications in hypertension and endothelial dysfunction." (PMID 35571179, 2022). "HMGB1, which is an inflammatory cytokine, interacts with the Receptor for Advanced Glycation products (RAGE) which leads to oxidative stress and inflammatory response, which causes endothelial dysfunction." (PMID 32133250, 2020). "In this study, we investigated whether the HMGB1/RAGE signaling pathway contributes to endothelial dysfunction induced by UA." (PMID 28116308, 2017). "HMGB1 is a proinflammatory cytokine that plays a critical role in endothelial dysfunction." (PMID 25303153, 2014). "Hence, in the present study, we tested whether TMAO upregulates HMGB1 expression in endothelial cells and contributes to endothelial dysfunction." (PMID 31336567, 2019). "RAGE activation by extracellular HMGB1 leads to nuclear translocation of NF-κB in HUVECs and further promotes the production and release of proinflammatory mediates and contributes to the amplification of the inflammatory response and finally induces endothelial dysfunction." (PMID 28116308, 2017). "HMGB-1 is a well-known non-AGE ligand for RAGE and can induce endothelial dysfunction; therefore, HMGB-1 may cause increased ROS generation in late EPCs." (PMID 26798412, 2016). "Signaling effect of HMGB-1 on endothelial dysfunction is still largely unknown." (PMID 25490770, 2014). "The binding of HMGB1 to receptors such as TLR2, TLR4, and RAGE triggers inflammatory pathways that contribute to endothelial dysfunction and vascular inflammation." (PMID 40361188, 2025). "TMAO also induces endothelial dysfunction by disrupting junction proteins, activating the NLRP3 inflammasome to release high-mobility group box 1 protein (HMGB1), and altering endothelial permeability." (PMID 40777990, 2025). "Our previous studies also showed that an anti-HMGB1 antibody attenuated RAGE expression and its downstream effector NF-κB activation in Ang II-induced endothelial dysfunction and cardiomyocyte hypertrophy." (PMID 33198253, 2020). "In the recent past, scientific research has led to the identification of different serological markers of endothelial dysfunction, of which the most important elevated findings in subjects with NAFLD were high mobility group box 1 (HMGB-1), Endocan, and anti-endothelial cell antibodies (AECAs)." (PMID 31737175, 2019). "HMGB1 is an inflammatory cytokine that interacts with the receptor for advanced glycation end products (RAGE), inducing an oxidative stress and inflammatory response, which leads to endothelial dysfunction." (PMID 28116308, 2017). "The HMGB1 leads to endothelial dysfunction; it is an inflammatory cytokine which, when binds with the receptor for advanced glycation end-products (RAGE), induces an oxidative stress and inflammatory response, which leads to endothelial dysfunction." (PMID 29492061, 2017). "Moreover, HMGB1, a key mediator of TMAO-induced endothelial dysfunction, might serve as a significant target for treating endothelial dysfunction and its related cardiovascular diseases." (PMID 40777990, 2025).
liver cancer (36 papers, 2014 to 2025). An epithelial or non-epithelial malignant neoplasm that arises from the liver. "Meanwhile, PCNA (a protein recently related with tumor formation) and HMGB-1 (acts extracellularly as a cytokine to promote cell migration) had been shown to be associated with liver cancer as well." (PMID 30356380, 2018). "The HMGB1 signalling pathway is also reported to be associated with growth and metastasis of liver cancer and to be a potential therapeutic target for this cancer." (PMID 26042604, 2015). "For example, it inhibits HSPA4 and HSP90AA1 protein expression in liver cancer cells, while downregulating HMGB1, IL6, and TNF levels in ischemia–reperfusion rats." (PMID 39759512, 2024). "In, 2013, it was reported that the addition of exogenous HMGB1 to H22 liver cancer cells, acting on RAGE and through the NF-kB pathway, increases the expression of matrix metalloproteinase 9 (MMP9), promoting the invasion of H22 cells." (PMID 38529373, 2024). "This miRNA inhibits liver cancer cell proliferation by downregulating HMGB1 and modulates several cell death responses." (PMID 39759512, 2024). "Our study showed that the expression of β-catenin, COX-2, and HMGB1 increased during the progression of liver cancer and that the expression was higher in cancerous regions than in paracancerous regions." (PMID 36937390, 2023). "Evidence that HMGB1 (high-mobility group box 1) has enhanced expression in HBV-related liver cancer has been presented, accounting for the epithelial–mesenchymal transition (EMT) and angiogenesis in cancer." (PMID 36142450, 2022). "HMGB1 has been reported to play an important role in multiple pathological processes of liver cancer, including proliferation, migration, cell differentiation, and the inflammatory response." (PMID 35480307, 2022). "The correlation between the high expression of HMGB1 and tumor grade and staging has also been reported in gastric adenocarcinomas and liver cancer." (PMID 34257571, 2021). "As another important factor in the pathogenesis of liver cancer, HMGB-1 can inhibit cell apoptosis and promote tumor invasion and metastasis." (PMID 32754037, 2020). "Previous studies in patients with primary liver cancer have shown that expression of high mobility group box-1 (HMGB1) in local liver tissues can rise dramatically in a few hours after TACE." (PMID 33473353, 2020). "First, we identified that HMGB1 was significantly up-regulated in both cisplatin-treated liver cancer cells and tumor tissues; this, also correlated with poor prognosis in patients with HCC." (PMID 32328193, 2020). "We also examined the expression level of HMGB-1, the expression of which had been demonstrated to control liver cancer initiation via YAP-HIF1α pathway." (PMID 30356380, 2018). "On the one hand, HMGB1 may promote tumor formation, for example, by playing an important role in regulating mouse oval cell activation and liver cancer development related to inflammation." (PMID 40495163, 2025). "Ethyl pyruvate (EP), an inhibitor of HMGB1, enhances apoptosis in liver cancer cells." (PMID 38529373, 2024). "Its overexpression suppresses the invasion and metastasis of liver cancer cells by targeting HMGB1." (PMID 39759512, 2024). "miR-200a-3p shows low expression in liver cancer, while HMGB1 is highly expressed." (PMID 39759512, 2024). "In liver cancer, EP inhibits the expression of HMGB1 and RAGE." (PMID 38529373, 2024). "In addition, it has been reported that the serum HMGB1 level in HCV-infected patients with liver cancer is significantly higher than that in healthy individuals." (PMID 36139393, 2022). "This study reveals that DENV2 induces autophagy in lung and liver cancer cells and showed that DENV2 capsid, envelope, NS1, NS3, NS4B and host cell proinflammatory high mobility group box 1 (HMGB1) proteins associated with autophagosomes which were purified by gradient centrifugation." (PMID 34696464, 2021).
liver cancer (continued). "However, this is not a phenomenon of malignant B-cells, because other live tumor cells, such as colon, gastric and liver cancer cells are also able to secret HMGB1." (PMID 26315113, 2015). "Knockdown of HMGB1 gene also inhibited liver cancer growth and metastasis." (PMID 25356587, 2014). "It has been documented that HMGB1 plays a key role in biological processes that contribute to characters of chronic liver diseases and may serve as a marker for monitoring the surgical course in patients undergoing surgery for liver cancer." (PMID 35046917, 2021). "One such lncRNA, TP73-AS1, targets miR-200a to inhibit its expression, thereby upregulating HMGB1/RAGE expression and promoting proliferation in liver cancer cells." (PMID 38529373, 2024). "EP reduces p-AKT expression through the HMGB1-RAGE axis and increases the Bax/Bcl-2 ratio, promoting apoptosis in liver cancer." (PMID 38529373, 2024). "AMPK, inflammation-related β-catenin, COX-2, HMGB1, hypoxia-related HIF-1α, and cellular senescence-related p16 are all important in the development of liver cancer." (PMID 36937390, 2023). "Studies have shown that HMGB1 can form an RNA-RNA crosstalk network with RICTOR, promote the progression of liver cancer by promoting glutamine metabolism, and enhance the activity of PD-L1 exosomes to reduce tumor immunotherapy." (PMID 36267972, 2022). "To further examine the expression levels of HMGB1 and RICTOR in the experimental context, we utilized the DEN + CCl4-induced liver cancer model in C57 mice." (PMID 34916485, 2021). "While our study was only limited to liver cancer, and lack of deeper mechanistic knowledge of the regulatory relationship between HMGB1 and chemokines from HCC." (PMID 34497155, 2021). "Furthermore, we detected HIF-1α and HMGB1 protein levels in SMMC-7721 and Huh7 human liver cancer cells after TNF-α (10ng/mL) treatment." (PMID 32328193, 2020).
renal fibrosis (36 papers, 2014 to 2025). A final common manifestation of a wide variety of chronic kidney diseases characterized by glomerulosclerosis and tubulointerstitial fibrosis. "In conclusion, on 2 consecutive days in a 100 mg/kg STZ-induced renal fibrosis mouse model, our results demonstrate that aggravated renal fibrosis is positively associated with the activation of HMGB1/TLR2/4 signaling." (PMID 36448056, 2022). "Cumulatively, the results demonstrated that HMGB1 expression was well associated with STZ-induced renal fibrosis after 2 consecutive days of 100 mg/kg STZ injection intraperitoneally." (PMID 36448056, 2022). "Furthermore, CIH has been demonstrated to induce renal fibrosis, possibly associated with the release of high-mobility group box 1 (HMGB1) following RTEC pyroptosis, which triggers the migration and recruitment of monocytes/macrophages." (PMID 39595526, 2024). "In renal fibrosis, the loss of Chop gene represses Hmgb1/TLR4 signal pathway, leading to repressed NF-κB transcriptional activity along with suppressed IL-1β production, and reduced TGF-β1 production and PI3K/Akt activity to attenuate the development of fibrosis." (PMID 36357371, 2022). "Although Chop deficiency did not affect UUO-induced TLR2 and RAGE expression, UUO induced a significant upregulation for both TLR2 and RAGE, indicating that additional factors other than CHOP-associated HMGB1 are also implicated in the pathogenesis of renal fibrosis." (PMID 26247732, 2015). "Deficiency of CHOP can ameliorate renal ischemia-reperfusion injury in mice, and prevents UUO-induced renal fibrosis by attenuating fibrotic signals derived from HMGB1/TLR4/NF-κB/IL-1β signaling." (PMID 41280890, 2025). "Our findings indicate that LM49 can effectively ameliorate UUO‐ and FA‐induced renal fibrosis, which is connected to the suppression of HMGB1‐induced inflammation and TEC necrosis." (PMID 39566909, 2025). "Collectively, our findings show that LM49 treatment can ameliorate renal fibrosis through inhibition of HMGB1‐mediated inflammation and necrosis via binding to Hsp90α, providing strong evidence for its anti‐inflammatory and anti‐fibrotic actions." (PMID 39566909, 2025). "On the other hand, circulating HMGB1 exacerbates renal fibrosis by promoting renal epithelial cell and macrophage trans-differentiation, thereby promoting renal disease progression." (PMID 38481996, 2024). "On the other hand, CHOP ablation has been reported to attenuate renal fibrosis via the downregulation of HMGB1/TLR4/ NF-κB pathway." (PMID 39682695, 2024). "In the unilateral ureter obstruction (UUO)-induced renal fibrosis model, macrophages exhibit a rise in HMGB1 expression which accounted for a phenotypic switch to pro-inflammatory M1 subtype." (PMID 39682695, 2024). "The severity of renal fibrosis is positively correlated with the activation of HMGB1/TLR2/TLR4 signaling." (PMID 37781525, 2023). "To further explore the role of HMGB1 in renal fibrosis, we examined the effects of Hmgb1 knockdown in BUMPT cells during RLDC treatment." (PMID 37284446, 2023). "Released HMGB1 can ultimately lead to renal fibrosis by triggering inflammation and activating TGF-β1/Smad2/3 signaling." (PMID 37256223, 2023). "In the present study, we refined the STZ-induced diabetic mouse model by administering different frequencies and doses to observe the effect of HMGB1 on renal fibrosis in DKD mice at different time points." (PMID 36448056, 2022). "This study demonstrates that the progression of renal fibrosis is related to the activation of HMGB1 in the STZ-induced diabetic mouse model." (PMID 36448056, 2022). "Cumulatively, the results indicated that the activation of HMGB1-TLR 2/4 signaling promoted renal fibrosis via NF-κB-mediated production of proinflammatory cytokines." (PMID 36448056, 2022). "miR-92d-3p suppressed the progression of DN renal fibrosis by inhibiting the activation of the C3/HMGB1/TGF-β1 pathway and EMT." (PMID 33729484, 2021).